EGFR (epidermal growth factor receptor)
Diseases named in the same sentence as EGFR in open-access papers (continued):
Sharing a sentence is not in itself a finding about the gene and the disease.
cancer (continued). "Mechanistic studies revealed FS targets key molecules (STAT3, EGFR, ESR1, PTGS2, NF-κB1, and JUN), modulating PI3K-Akt, MAPK and cancer-related pathways." (PMID 40649400, 2025). "In colorectal cancer, NSD2 overexpression accelerates cell proliferation and migration by increasing global H3K36me2 levels and several cancer-promoting genes, such as ADAM9, EGFR, and MET." (PMID 41301842, 2025). "The results showed that pathways that are enriched with hub genes are pathways in cancer, PI3K-Akt signaling pathway, MicroRNAs in cancer, EGFR tyrosine kinase inhibitor resistance, and Proteoglycans in cancer." (PMID 39863836, 2025). "Key signaling pathways enriched in the analysis include Pathways in cancer, PI3K/Akt signaling, EGFR tyrosine kinase inhibitor resistance, endocrine resistance, and central carbon metabolism in cancer." (PMID 40444042, 2025). "Variability in trial designs (e.g., combination therapies, line of treatment) and patient populations (e.g., EGFR/ALK status, cancer grading) further contributed to heterogeneity." (PMID 41000392, 2025). "Targeting cell surface receptors offers key advantages, including the ability to disrupt dysregulated pathways driven by oncoproteins such as EGFR, HER2, VEGFR, and PD-PDL1, which are essential for cancer cell growth and survival." (PMID 39857961, 2025). "Petosemtamab (MCLA-158) is a human, common light-chain IgG1 bispecific antibody that simultaneously targets the EGFR and the leucine-rich repeat-containing G-protein-coupled receptor 5 (LGR5), a cancer stem cell marker." (PMID 41375018, 2025). "Petosemtamab targets both EGFR as well as leucine-rich repeat-containing G-protein coupled receptor 5 (LGR-5), which is known to be upregulated in cancer and is also pro-oncogenic by encouraging cell proliferation and reducing apoptosis." (PMID 40868227, 2025). "PTK2B promotes tumorigenesis, migration, and invasion by activating several signaling pathways, including Wnt/β-catenin, PI3K/Akt, MAPK/ERK, and TGF-β/EGFR/VEGF, making it a promising target for cancer therapy." (PMID 41166024, 2025). "To consolidate our findings, we analyzed BNIP3 and EGFR, two alternative target genes of HIF-1 and HIF-2, respectively, which are relevant to cancer biology." (PMID 40918648, 2025). "Molecular docking studies revealed that the newly designed compounds exhibited better binding affinities, ranging from −7.2 to −9.8 kcal/mol, to key cancer-related targets (CDK2, EGFR, and Tubulin)." (PMID 40526618, 2025). "Based on multiple ML algorithms, we identified Hub-EGFR.Sig and found that it had an extensive relationship with the TIME and prognosis in pan-cancer." (PMID 40574864, 2025). "This study paved the way for the use of the mAb-IR700 conjugate in human cancer therapy with NIR-PIT, targeting neoplastic cells bearing the EGFR antigen." (PMID 40574027, 2025). "Osimertinib, a third‐generation of EGFR TKI, induced higher CD47 expression in EGFRmut NSCLC HCC827 and NCI‐H1975 cells via NF‐κB signaling, and it also reduced PD‐L1 expression in cancer cells." (PMID 40859900, 2025). "They then tested the effect of this HCAA on the epidermal growth factor receptor (EGFR), a tyrosine kinase that is overexpressed in certain cancer types." (PMID 40364401, 2025). "Mutant EGFR and KRAS both indirectly regulate cancer metabolism by activating downstream signaling pathways for metabolic regulation including Akt, MYC, and mTORC1, which in turn regulate practically every metabolic pathway in the cell." (PMID 39796781, 2025). "This co-targeting approach has shown promise in in vitro cancer models, including OC and triple negative breast cancer (TNBC) with an anti-EGFR/VEGFR2 BsAb." (PMID 40969763, 2025). "As a consequence, tailored medicines that precisely block EGFR and VEGFR2 have been developed to treat some forms of cancer, including non-small cell lung cancer and colorectal cancer." (PMID 41145684, 2025).
cancer (continued). "The Warburg effect, marked by enhanced glycolysis and diminished oxidative phosphorylation, is a defining feature of cancer metabolism and is modulated by SPINK-mediated EGFR signalling." (PMID 40872585, 2025). "Mechanistically, agrin mechanoactivates EGFR through epidermal growth factor (EGF)‐dependent and independent modes, thereby sensitizing its activity toward localized cancer cell‐ECM adherence and bulk rigidity by fostering interactions with integrin β1." (PMID 40165020, 2025). "In vitro studies showed that adding isolated human immune cells notably enhanced amivantamab-mediated EGFR and MET downregulation, resulting in dose-dependent cancer cell death." (PMID 40002883, 2025). "To complement the experimental cytotoxicity screening, we conducted in silico molecular docking studies to predict the binding interactions of these derivatives with the key cancer-related targets, including Topoisomerase II, VEGFR2, c-Met, EGFR, and ERα." (PMID 40610494, 2025). "EGFR activation stimulates the PI3K/Akt pathway, thereby contributing to the molecular pathogenesis of diverse cancers." (PMID 41293238, 2025). "This study introduces a safe and effective intratumoral EGFR‐targeted CRISPR‐LNP delivery strategy for knocking out SOX2, which is a cancer‐specific gene." (PMID 39736115, 2025). "In the constructed pan-cancer drug–gene network, the top hub gene of the network was mTOR, which interacted with 45 drugs, followed by BCL2, STAT3, and EGFR." (PMID 40293950, 2025). "In these cells, UA induces apoptosis, arrests the cell cycle, and inhibits cancer cell proliferation by downregulating key proteins such as STAT3, EGFR, and cyclin D1." (PMID 40141751, 2025). "TFAP2A modulates key oncogenes, including EGFR, and contributes to therapy resistance by promoting epithelial-mesenchymal transition (EMT) and cancer stem cell properties." (PMID 41323280, 2025). "Acting through both autocrine and paracrine mechanisms, TGF-α activates EGFR-dependent signaling pathways - such as the Ras/Raf/MEK/ERK and PI3K/AKT/mTOR cascades - that support cancer cell proliferation, survival, and therapeutic resistance." (PMID 40843353, 2025). "This dual role of TGF-β complicates its relationship with EGFR-TKI treatment, as the cancer stage and specific tissue context can influence its effects." (PMID 40002883, 2025). "Erlotinib is a tyrosine kinase inhibitor (TKI) that targets the epidermal growth factor receptor (EGFR), a receptor necessary for cancer growth and survival." (PMID 40282495, 2025). "In cancer, altered PTEN expression or activity can affect the response to EGFR inhibitors by modulating various signaling pathways that regulate cell survival and apoptosis." (PMID 40129883, 2025). "The EGFR is one of the most studied growth factor receptors, which can form one type of homodimer and three types of heterodimers constituted by EGFR and HER2, thus regulating critical cellular processes and serving as an important target for cancer therapy." (PMID 40289109, 2025). "Previous studies demonstrated that CD44 interacts with EGFR potentiating MAPK/ERK pathway 13, 29 and TGFβR1 30 in human cancer cells." (PMID 40860188, 2025). "This review discusses structural modifications in vitamin D3, their influence on VDR binding, transcriptional activity, and calcium homeostasis, along with their role in targeting pathways like EGFR, KRAS, and Hedgehog in cancers." (PMID 40299638, 2025). "The development of dual inhibitors such as 2‐mercaptobenzoxazole derivatives, which target EGFR, HER2, VEGFR2, and CDK2, exemplifies the growing trend toward multitargeted cancer therapies designed to overcome a range of resistance mechanisms." (PMID 41523619, 2025). "For example, CAFs have been shown to confer resistance to EGFR TKIs and sole presence of CAFs from gefitinib-resistant tumors can induce EMT and resistance to TKIs in previously sensitive cancer cells." (PMID 40524071, 2025).
cancer (continued). "In cancer, EGF and EGFR are often found to be abnormally overexpressed, and EGFR is currently overexpressed in 54-74% of cervical cancer." (PMID 40302795, 2025). "Intriguingly, the high-throughput anti-cancer compound screening assays demonstrated that TFF3 inhibition by AMPC synergized most effectively with compounds targeting four distinct RTKs, EGFR, VEGFR, c-KIT, and c-MET in MDA-MB-361 and BT474 cells." (PMID 39920140, 2025). "Nuclear EGFR increases cyclin D1, inducible nitric oxide synthase (iNOS), and MYBL2 (B-Myb), all of which are involved in cancer proliferation." (PMID 39948411, 2025). "It accomplishes this by downregulating essential molecules involved in various signaling pathways that favor cancer cell survival and proliferation, EGF and its receptor EGFR, along with key downstream effectors such as PKB and GSK-3β." (PMID 40656954, 2025). "Monophasic tumors are characterized by higher expression of cancer-related genes CDKN2A, EGFR, and PDGFRL, which can be considered as potential targets for treatment." (PMID 41155410, 2025). "Correlation analysis demonstrated that the relationship between Hub-EGFR.Sig and DSS or PFI varied in different cancers." (PMID 40574864, 2025). "The CRYSTAL study was pivotal in showing the survival advantage of adding an anti-EGFR mAb to standard FOLFIRI chemotherapy, but only in those patients with molecularly selected cancers." (PMID 40940907, 2025). "Protein phosphatase 2A plays a central role in modulating multiple signaling pathways, including PI3K, EGFR, Myc, WNT, JAK/STAT, RAS/MAPK, and NF-κB, which are frequently dysregulated in cancer." (PMID 41146310, 2025). "In parallel, the extensive use of Drosophila melanogaster and Caenorhabditis elegans, two exquisitely informative model systems, allowed to better characterize the EGFR‐RAS‐MAPK signaling pathway in development and cancer growth." (PMID 39470386, 2025). "Epidermal Growth Factor Receptor (EGFR) inhibitors, such as Erlotinib and Gefitinib, block the EGFR pathway, essential for cancer cell proliferation." (PMID 40277781, 2025). "To examine potential effects of cancer treatment resistance on BA sensitivity, we established A549 cells resistant to osimertinib, a tyrosine kinase inhibitor (TKI) for the epidermal growth factor receptor (EGFR) administered for the treatment of NSCLC." (PMID 40316727, 2025). "EGFR and VEGF have been reported to be the two important signalling pathways involved in the proliferation of HPV-related cancers." (PMID 40028476, 2025). "Comparative expression of the genes involved in upstream (epidermal growth factor receptor, EGFR) and downstream (epithelial–mesenchymal transition (EMT) and mesenchymal–epithelial transition) cancer pathways was targeted for investigation." (PMID 41226554, 2025). "By modifying important genes and proteins involved in cancer resistance and treatment, CAPE is a therapeutically useful chemical that helps AZD9291 treat EGFR-TKI-resistant cells." (PMID 40728967, 2025). "The epidermal growth factor receptor (EGFR) pathway intersects with the insulin growth factor (IGF-1) pathway, leading to the proliferation and migration of cancer cells." (PMID 40805279, 2025). "Phase separation of these proteins would be regulated by kinases, including CDK1, CDK2, and EGFR, and transcription factors, including ZNF407, ZNF318, and MGA proteins, to play functions in cancer." (PMID 41154723, 2025).
cancer (continued). "It suppresses EGFR‐mediated activation of the PI3K/AKT and MAPK pathways, reducing cancer cell proliferation and inducing apoptosis in lung, breast, and colon cancer models." (PMID 40115248, 2025). "When activated by ligands (e.g., EGF), EGFR triggers key pathways including RAS-RAF-MAPK and PI3K-AKT, which drive cancer cell proliferation and metastasis." (PMID 40783393, 2025). "Here, we showed that, instead of inhibiting EGFR or EGFR phosphorylation, CAP selectively turned on the ferroptotic program of cancer cells by potentiating EGFR phosphorylation at Y1068 and, concomitantly, enhancing cellular redox level." (PMID 39781456, 2025). "EGFR and VEGFR-2 have been recognized as potential therapeutic targets in the battle against cancer." (PMID 41357101, 2025). "These included some notable oncogenes known to be drivers in the found cancer types, such as PIK3CA in BRCA, BRAF in SKCM, and EGFR in LGG and LUAD, and KRAS across several cancers including PAAD, LUAD and COAD." (PMID 41415395, 2025). "The compounds were tested against various cancer cell lines, including HCC827 (EGFR Del E746-A750), NCI-H1975 (L858R/T790M), and A549 (wild-type EGFR), as well as normal BEAS-2B bronchial epithelium cells." (PMID 40430417, 2025). "Critical targets such as TNF, EGFR, ESR1, HIF1A, HSP90AA1, and SRC were involved in pathways including chemical carcinogenesis, PI3K‐Akt signaling, proteoglycans in cancer, receptor activation in chemical carcinogenesis, and immunomodulation." (PMID 40144560, 2025). "Both downstream activation through alternative pathways and upstream activation occurs after inhibition of KRAS G12C, which correlates with the increased expression levels of EGFR, HER2, FGFR, and c-MET observed in cancer cells." (PMID 40597785, 2025). "To mimic the natural development of EGFR inhibitor resistance in patients, we implanted the HCC827 control and CMTM4 KO cancer cells in animals and treated with gefitinib." (PMID 39948411, 2025). "EGFR is known to regulate several downstream signaling pathways such as ERK, PI3K/AKT and JAK/STAT, which all play a crucial role in the regulation of cancer stemness, angiogenesis and metastasis." (PMID 39888904, 2025). "For instance, EGFR signaling in macrophages activates NF‐κB and MAPK pathways to enhance pro‐inflammatory responses or activates AKT/CREB to promote M2 polarization in cancer." (PMID 40859900, 2025). "Due to its covalent bonding to the EGFR-AKT activation site, nanomolar range (1 and 10 nM) of afatinib was found to effectively attenuate EGFR activation in cancer cells." (PMID 40444141, 2025). "Among the different HERs, EGFR and HER-2 are highly expressed in various cancer types including breast cancer." (PMID 40284015, 2025). "EGFR inhibitors (e.g., erlotinib, gefitinib) inhibit ATP binding to the tyrosine kinase domain of EGFR, preventing receptor autophosphorylation, thereby inhibiting downstream signaling through the RAS-RAF-MEK-ERK and PI3K-AKT-mTOR pathways in cancer cells." (PMID 40872476, 2025). "According to overexpression of epidermal growth factor receptor (EGFR), same study also reveals altered kinase signaling network involving MAP2K2 to regulate the aberrant changes in the recurrent cancer cells." (PMID 41197182, 2025). "It is crucial to identify natural and dual HER2 and EGFR inhibitors in the fight against HER2-positive and EGFR-driven cancers." (PMID 40082669, 2025). "The use of clinically relevant cancer models adds translational value, while the integration of functional and molecular endpoints allows for a more nuanced understanding of how cytoskeletal disruption and EGFR inhibition may interact to impair cancer cell survival." (PMID 41401147, 2025). "In cancer treatment, S. cerevisiae enhances the integrity of enterocyte tight junctions, influences host cell signaling, reduces ERK1/2 and EGFR signaling activities, and deactivates tyrosine kinase receptors." (PMID 39998665, 2025).
cancer (continued). "FRK has been shown to act as a growth inhibitor in several cancer cell lines, in part by inhibiting signalling pathways such as JAK/STAT, MAPK, Akt and the EGFR pathway." (PMID 39009935, 2025). "The human epidermal growth factor receptors (EGFR, HER2, HER3, and HER4) are tyrosine kinase receptors expressed in normal tissues and various cancers." (PMID 40243654, 2025). "Lately, bispecific antibody drug conjugates targeting EGFR and MET have also attracted attention in the pharmaceutical industry with multiple drugs of this kind already in early phase trials for MET-aberrant cancers." (PMID 41368576, 2025). "The KEGG analysis results showed that CS likely exerted its anti-RIF effects through signaling pathways such as PI3K-Akt, Proteoglycans in cancer, AGE-RAGE, and EGFR." (PMID 41142245, 2025). "Alterations in upstream proteins, such as the epidermal growth factor receptor (EGFR), can activate the mTOR/Akt pathway, leading to increased cancer cell survival by inhibiting apoptosis." (PMID 40287470, 2025). "The epidermal growth factor receptor (EGFR) is involved in the development of morphine tolerance in various rodent models, including the cancer-induced bone pain rat model and the spinal nerve ligation rat model." (PMID 41282620, 2025). "The reduced copper content not only inhibits tumor neovascularization, but also inhibits the phosphorylation of EGFR and STAT3, promotes ubiquitin-mediated degradation of PD-L1 and inhibits PD-L1 transcription, eventually blocks cancer immune escape." (PMID 39744687, 2025). "Our BsAb inhibited EGF-induced activation of EGFR in CaOV3 and SKOV3, as well as blocked EGF-induced activation of VEGFR2 in CaOV3 and PA-1 OC cancer cell lines." (PMID 40969763, 2025). "While KMD5A knockout significantly reduced the number of DTPs and DTEPs upon EGFR TKI treatment, transient expression of KDM5A decreased cancer cell sensitivity to treatment." (PMID 41304766, 2025). "Our study identified core genes (ALB, BCL2, EGFR, IL-6, and STAT3) enriched in cancer pathways, suggesting a potential link between cancer-related metabolic dysregulation and fatigue." (PMID 40435272, 2025). "In particular, PLA nanoparticles readily conjugate targeting ligands, such as antibodies or peptides, to their surface, enabling highly efficient selective drug delivery to cancer cells that overexpress specific receptors, such as HER2 or EGFR." (PMID 41155989, 2025). "One example includes peptides targeting HER2 (human epidermal growth factor receptor 2), EGFR (epidermal growth factor receptor), and VEGFR (vascular endothelial growth factor receptor), which are often overexpressed in various cancer types." (PMID 41012460, 2025). "The highest enrichment results found through the three databases also encompass a large number of signaling pathways associated with cell growth and proliferation, such as EGFR, ERBB, MAPK, PI3K-Akt, and Ras considered as main actors in cancer context." (PMID 40920362, 2025). "The two main angiogenic factors that cancer cells release are vascular endothelial growth factor (VEGF) and epidermal growth factor receptor (EGFR)." (PMID 41252403, 2025). "Many studies have provided ample evidence suggesting the presence of aberrant signaling by the epidermal growth factor receptor (EGFR) (the ErbB tyrosine kinase receptor (TKR)), which is correlated with cancer progression." (PMID 40002260, 2025). "CAFs drive resistance in EGFR-mutant NSCLC by promoting EMT and secreting resistance-inducing factors such as HGF, IL-6, and kynurenine, activating pro-survival pathways in cancer cells." (PMID 40002883, 2025). "For cancers driven by specific oncogenes, such as BRAF or EGFR, antioxidants can reduce oxidative stress-induced pathways that contribute to resistance." (PMID 40563308, 2025).